KRAS (KRas proto-oncogene, GTPase)
Diseases named in the same sentence as KRAS in open-access papers (continued):
Sharing a sentence is not in itself a finding about the gene and the disease.
tumor (continued). "Mechanistic analysis revealed lactic acid derived from mutant KRAS‐expressing tumor cells sensitized tumor‐specific cytotoxic CD8+ T‐cells to activation‐induced cell death via NF‐κB inactivation; this may underlie the inverse association between intratumoral cytotoxic CD8+ T‐cells and KRAS mutation." (PMID 36599679, 2023). "Studies have reported that the PI3K pathway can be activated by signalings other than KRAS, and that amplification and the overexpression of the transcriptional coactivator Yap1 can also drive KRAS-independent PDAC tumor maintenance." (PMID 36675641, 2023). "Hallmark gene sets demonstrated that the top upregulated pathways correlating with expression of the MESO EMT genes were TGF-β signaling, tumor angiogenesis, hedgehog signaling, IL-2-STAT5 signaling, KRAS, and hypoxia pathways." (PMID 36901697, 2023). "Oncogenic KRAS contributes to PDAC pathology by promoting malignant transformation, tumor maintenance, metabolic rewiring, metastasis, desmoplasia, and immune cell dysregulation." (PMID 36719686, 2023). "At molecular analysis of KRAS and NRAS in FFPE tumor tissue biopsies, 41 out of 62 patients (66.1%) harbored RAS mutations, while 21 (33.9%) were classified as WT." (PMID 37296579, 2023). "Here, we sought to elucidate the involvement of mutant KRAS in cytotoxic CD8+ T‐cell fate decisions and to uncover its functional effects on tumor immune escape." (PMID 36599679, 2023). "The expression of CXCL8 was increased in CK7- and phospho-Smad3-positive acinar-type tumor tissue compared with solid-type tumor tissue in the A549 xenograft model, as well as in human LADC tissue and mutant KRAS-driven mouse lung cancer tissue." (PMID 37174001, 2023). "For half of the biomarkers (AKT, ALK, BRAF, EGFR, Hedgehog, HER2, KRAS, MSI, NTRK, and ROS1), depending on the tumor type, the response rate ranged from 0 to 100%." (PMID 36639625, 2023). "As expected, similar results were obtained for KRAS signaling genes, which like EMT genes, are highly enriched in tumor versus non-tumor PDAC." (PMID 37170215, 2023). "For CRCs, tumor anatomic site, stage, and molecular profiles, specifically microsatellite instability (MSI), KRAS, BRAF, and PI3K, aid in designing treatments." (PMID 36916704, 2023). "Patients with KRAS, NRAS, PIK3CA and BRAF wild-type tumours were randomised between the pan-HER inhibitor AZD8931 and placebo." (PMID 35256486, 2023). "AMG 510 treatment for 8 days significantly suppressed tumor growth, inhibited KRAS activity, STAT3 phosphorylation, and CD47 expression, and stimulated miR-34a expression in tumor tissues." (PMID 36413402, 2023). "Our study also showed high distribution of KRAS mutants in AIS and MIA cases where imply slow tumor growth with good prognosis." (PMID 36918771, 2023). "7/8 (88%) methods found mutually exclusive alterations in KRAS, NRAS or BRAF as a predictive biomarker, from which one, two and four methods proposed this marker in conjunction with tumour sidedness, CMS and across all patients, respectively." (PMID 37666855, 2023). "Further in vivo verification of the anti‐tumor effect of co‐targeting RAD51 and KRAS is required in the future." (PMID 36262061, 2023).
tumor (continued). "Upon KRAS activation, cyclin D/CDK4/6 complex get activated, and subsequently phosphorylates retinoblastoma (RB) and promotes tumor cells’ entry into S phase." (PMID 37221195, 2023). "To demonstrate the possibility of detecting and quantifying tumor DNA directly from the plasma of PDAC patients, we performed multiplex analysis of KRAS in 46 plasma samples." (PMID 36810451, 2023). "We have previously shown that the combination of TUSC2 and anti-PD1 inhibited tumor growth synergistically in subcutaneous and metastatic NSCLC KRAS mutant syngeneic mouse models." (PMID 35210547, 2022). "This evaluative process is essential to lay the groundwork for testing mechanism-based therapeutic strategies to thwart resistance and improve clinical outcomes for patients with KRAS G12C–driven NSCLC and potentially other KRAS-driven tumor types." (PMID 35166243, 2022). "Interestingly, when we combined the KRAS mutational status with RI, the patients with RAS-high/KRAS wt tumours had the same outcome as those with RAS-high/KRAS mut, confirming that the tumour progression driven by oncogenic RAS activity is independent of KRAS mutational status." (PMID 36163168, 2022). "Interestingly, in one these patients the driver mutation in the tumor was identified to be in PTPN11, in the same gene that frequently acquires somatic mutations leading to HS in BMDs; and in two other FA patients, mutations in the tumors were in KRAS, also identified in HS of BMDs." (PMID 36292578, 2022). "For example, mutant KRAS and MYC are known to trigger, beyond glucose and amino acid, also the rewiring of lipid pathways in a variety of tumour models." (PMID 35255936, 2022). "Oncogenicmutations in KRAS, a member of the RAS family of small GTPases, occur in 20-30% ofpatients with NSCLC and drive multipleprocesses that promote tumour development." (PMID 35930804, 2022). "For example, after inactivation of KRAS, a subpopulation of PDAC tumor cells relied on mitochondrial respiration and beta-oxidation to survive, which eventually led to tumor relapse." (PMID 35121743, 2022). "Sufficient tumor material was available from fourteen patients treated with certolizumab (14/18; 78%) for EGFR, KRAS, BRAF, ERBB2, and ALK testing and from ten patients (10/18; 56%) for NGS." (PMID 36241629, 2022). "In this study, pathological tumor size, tumor depth, and stage were correlated with preoperative MAF of KRAS, but it was unreliable to predict recurrence by detection of ctDNA with KRAS mutation in the perioperative period of colorectal surgery." (PMID 35312176, 2022). "Constitutive active KRAS signaling, for instance, switches tumor-suppressive EZH2 functions evident in early pancreatic carcinogenesis into tumor-progressive activities in advanced neoplasia." (PMID 35884510, 2022). "KRAS/STK11 aberrations, on the other hand, promote a so-called ‘cold tumor’ immune microenvironment, generally with limited PD-L1 expression and reduced infiltrating CD8+ T cells." (PMID 36077640, 2022). "Thus, it seems that Kim and Turrini’s cohorts are not comparable to ours, at least in terms of tumour grade, which might explain the different prognosis value of KRAS mutation presence in margins, which may be of clinical value for lower grade PDACs." (PMID 35194118, 2022). "This indicates that pancreatic ITPN cannot be considered as a KRAS-independent entity, also taking into account that MAPK-pathway can be activated in this tumor type also through BRAF alterations (case #7)." (PMID 36056133, 2022). "In neoantigen vaccine studies, PD-1 ICB improved MC38 tumor control elicited by nanoparticle complexes of CpG and neoantigens, including the MC38 neoantigens Adpgk and Copg1 and mutant KRAS neoantigens." (PMID 35651800, 2022).
tumor (continued). "Based on these results, DXI was more likely to affect the tumor-promoting interactions of DX2 and KRAS." (PMID 35546148, 2022). "Tumor malignant phenotype related IGFBP2 and KRT18 were significantly enriched in KRAS-Mut subtype, whereas neutrophils and macrophages related CD177, MMP1 and ARG1 were enriched in WT subtypes." (PMID 35836817, 2022). "A similar pattern was observed in C3L-01160, with KRAS VAF scores of 29.5% in bulk 51.8% in cored, and 30.6% in LMD tumor tissues, respectively, representing 59.0%, 100.0%, and 61.2% neoplastic cellularity in the bulk, cored, and LMD samples." (PMID 36266629, 2022). "Administration of R-IMPP to ApcMin/+KrasG12D/+Villin-Cre (50 mg/kg, i.p., 3 times/week) also significantly suppressed tumor number (P < 0.01) and load (P < 0.01), validating its efficacy in spontaneous APC/KRAS-mutant CRC." (PMID 35803966, 2022). "BI-3406 requires tumor cells in 3D aggregates for activity, an arrangement that is characterized by increased MEK-ERK activity and higher dependency on KRAS activity." (PMID 36048281, 2022). "With IPMN progression, tumor stemness increased continuously, and KRAS, ERBB3, RUNX1, and ELF3 are essential driver genes affecting tumor stemness." (PMID 36090038, 2022). "The unique expression pattern of ADM as an intermediate state suggests a dynamic transition between tumor and acinar fates and progression towards PDAC via acquisition of a driver KRAS event." (PMID 35995947, 2022). "In the majority of tumor types, NMNGs had a positive correlation with TNFA signaling via NFKB, KRAS signaling, interferon-gamma response, inflammatory response, and EMT." (PMID 36726460, 2022). "More potent KRAS G12C inhibitors rapidly emerged, and recently expanded phase I trials with sotorasib (AMG510) and adagrasib (MRTX849) have demonstrated tumor response rates of approximately 30% to 40% in lung cancer and a safe toxicity profile." (PMID 34990404, 2022). "Requesting KRAS makes sense “as a demand” for those patients with more aggressive tumours and should be considered today as an indispensable part of decision making before embarking on aggressive surgical therapy, while in other patients with specific criteria, the KRAS testing could be omitted." (PMID 35326950, 2022). "It was found that the activation of KRAS in gastric adenocarcinoma cells stimulates EMT and transforms EMT into CSCs, thereby promoting tumor metastasis." (PMID 35444235, 2022). "The tumor-promoting activity of YAP1 is attributed to the activation of TGF-β, Hedgehog, and KRAS signaling pathways." (PMID 36479120, 2022). "To investigate the relationship between hub genes and tumor growth regulation, we used the venny tool to integrate genes related to STAT and KRAS pathways." (PMID 36531013, 2022). "To assess the co-dependency of tumour cell lines on SHOC2 and RAS, we correlated chronos scores for SHOC2 and either MRAS or HRAS, KRAS or NRAS from all 1,061 tumour cell lines in DepMap." (PMID 35768504, 2022). "For example, in a mouse model with KRas-activated lung cancers, Tbk1 induces local immunosuppression by facilitating EGF-induced PD-L1 expression on tumor cells." (PMID 35395857, 2022). "The results acquired showed that increased expression levels of KRAS, MMP7, and CD44 promoted primary tumor and metastasis in CRC samples compared to adjacent normal samples." (PMID 35203586, 2022).
tumor (continued). "Pathological features that specialists were most unsure of included CDX2 status, EGFR status, Lymph node ratio, KRAS status, BRAF status and tumour budding." (PMID 35323316, 2022). "Using the Kaplan–Meier plotter bioinformatics tool, we identified higher expression levels of the KRAS, MMP7, and CD44 oncogenes in tumor and metastatic samples, compared to adjacent normal tissues." (PMID 35203586, 2022). "Currently, due to the reduced cost of genetic testing, the genotyping of tumor biomarkers such as BRAF, KRAS, NRAS, and MSI is possible." (PMID 36136880, 2022). "Tumor genotyping has now been incorporated in the clinical management of NSCLC with routine testing for EGFR, KRAS, BRAF, HER2, ALK, ROS-1, and RET to personalize first or second-line treatment." (PMID 35267628, 2022). "We investigated the anti-tumor efficacy of two KRAS inhibitors BI-3406 (KRAS::SOS1 inhibitor) and sotorasib (KRAS G12C inhibitor) alone or in combination with MEK1/2 inhibitor trametinib and/or PI3K inhibitor buparlisib in seven PDAC cell lines." (PMID 36139627, 2022). "We applied the TNM plot analysis to compare expressions of the KRAS, MMP7, and CD44 genes in normal, tumor, and metastatic CRC samples from RNA-Seq data." (PMID 35203586, 2022). "PYK2 (proline-rich tyrosine kinase 2) is a downstream mediator of the mutant KRAS signaling cascade and knockdown of PYK2 suppressed tumor growth in PDAC xenografts." (PMID 36048281, 2022). "The same group also showed that tumor growth was reduced by single targeting of ERBB2 in cetuximab-resistant, quadruple (i.e., KRAS, NRAS, BRAF, and PIK3CA) wt CRC patient derived xenografts with ERBB2 mutations." (PMID 35582524, 2022). "In an oncogenic KRAS-driven non-small cell lung cancer (NSCLC) mouse model, deleting Atg7 specifically in tumor cells reduced the tumor burden compared to that in mice with Atg7-expressing NSCLC." (PMID 35147163, 2022). "In conclusion, our results confirm a tumour suppressor role for both DUSP5 and DUSP6 in a clinically relevant model of mutant KRAS-driven oncogenesis." (PMID 35418690, 2022). "The findings underscore the differences in the prevalence rates of HRAS, KRAS, and NRAS according to tumor anatomical site and geographical region." (PMID 35600380, 2022). "In two additional PDX models, CRC001 (KRAS G12D MT) and CRC042 (KRAS G13D MT), less pronounced effects on tumor growth inhibiton were observed with the addition of AZD0156 to chemotherapy." (PMID 36309653, 2022). "We also evaluated the in vivo anti-tumor efficacy of DXI using HCC1588 (KRAS WT) and A549 (KRAS mutant) cell lines." (PMID 35546148, 2022). "KRAS activation leads to downstream signaling of three major pathways: the MAP kinase pathway, PI3K-AKT-mTOR pathway, and the tumour invasion and metastasis-inducing protein 1 (TIAM1-RAC) and RAS-related protein (RAL) pathways." (PMID 36284306, 2022). "Further, KRAS and c-MYC cooperate to drive an immunosuppressive TME in cancer development, leading to increase in macrophage infiltration of tumours and decrease in CD3+ T cells, B cells and natural killer (NK) cells." (PMID 36483040, 2022). "For example, the well-known downregulated let-7 family plays tumor-suppressive roles in OC by targeting oncogenes, such as c-MYC, HRAS, and KRAS, and cell cycle regulators." (PMID 35549643, 2022). "We further used Dunn’s test which revealed the significance of KRAS, MMP7, and CD44 expressions in promoting CRC tumor metastasis." (PMID 35203586, 2022).
tumor (continued). "In lung adenocarcinoma (LAC), KRAS and vascular endothelial growth factor (VEGF) receptor, NRP2, trigger MAPK/ERK/Gli1 signaling cascade to promote tumor progression." (PMID 35433472, 2022). "Currently, an IdyllaTM system for circulating tumor DNA in blood samples have already been developed for BRAF, KRAS, NRAS, and EGFR." (PMID 35474548, 2022). "Profound changes including increased tumor infiltration of T cells and upregulated MHC gene expression were observed in KRAS KO tumors." (PMID 35013174, 2022). "Thus, the reduction in downstream MAPK signaling from KRASG12V/K147D, especially since it did not impair self-association of KRAS, could be a consequence of the K147D mutation preventing these tumor-promoting posttranslational modifications." (PMID 36334633, 2022). "In vivo experiments further showed that downregulation of SLC7A5 inhibited tumor growth (sFigure 2) All of these results confirmed that SLC7A5, as an oncogenic gene, can mediate the development of KRAS mutant tumors." (PMID 36505791, 2022). "Some tumors had molecular aberrations in frequently altered genes in NSCLC such as ALK, EGFR, KRAS or ROS1, as determined with the TruSight Tumor 170 sequencing panel in-house." (PMID 35329826, 2022). "Their mechanism of action is based on the conversion of the preference of KRAS from GTP to GDP, holding a KRAS state from an active to inactive GDP-bound form and interrupting intracellular signaling and tumor cell growth." (PMID 36012655, 2022). "In addition, the preliminary results from the genomic mutation analyses demonstrated that each specific KRAS mutation from the tumor has been successfully detected in PDTs (data not shown), which suggests that our model is also suitable for screening targeted therapies." (PMID 35625840, 2022). "In summary, systemic treatment of NSCLC xenografts in mice with αEGFR-mAB-protamine-KRAS-siRNA-free SMCC-protamine nanostructures was successful, tumour-specific and tolerable." (PMID 35220407, 2022). "However, recent clinical screens found that amplification and/or activating mutations in the gene encoding KRAS decoupled the RAS-MAPK pathway activity from the MET receptor, constituting the most common form of resistance against MET-targeted therapies in METΔex14-presenting tumours." (PMID 35326531, 2022). "Recent in vivo data has suggested that the inhibition of KRAS G12C using AMG510 creates a pro-inflammatory tumor microenvironment, promoting the anti-tumor activity of immune cells alone and in combination with immune CPIs." (PMID 36185288, 2022). "Studies analyzing mutant KRAS CRC found that solute carrier family 25 member 22 (SLC25A22) promoted proliferation and migration of human CRC tumor cells which also resulted in the developments of metastases in CRC xenograft mouse models." (PMID 36090030, 2022). "In a xenograft model from KRAS-mutant H460 cells, NOP56 knockdown (shNOP56) only mildly inhibited tumor growth compared to control shRNA (shScrambled), as did rapamycin." (PMID 35039048, 2022). "We have focused on PIP-based KRAS inhibitor KR12 (pyrrole–imidazole polyamide indole-seco–CBI conjugate), which has been reported to exhibit tumor growth inhibition in a xenograft mouse model." (PMID 35205697, 2022). "Furthermore, although there is a correlation between KRAS mutations and OSBPL3, it is unclear whether OSBPL3 affects tumor biology regardless of KRAS status." (PMID 36517805, 2022). "The combination of anti-EGFR-mAB and siRNA targeting KRAS effectively suppressed KRAS protein expression in CRC cell lines, and reduced tumor volume and tumor weight effectively in a mouse implantation tumor model with cetuximab resistance mutation." (PMID 35953863, 2022).